CYFIP2 (cytoplasmic FMR1 interacting protein 2)
Diseases named in the same sentence as CYFIP2 in open-access papers (continued):
Sharing a sentence is not in itself a finding about the gene and the disease.
glioma (3 papers, 2022 to 2024). A benign or malignant brain and spinal cord tumor that arises from glial cells (astrocytes, oligodendrocytes, ependymal cells). "In this study, we demonstrate for the first time that the risk scores of NUDT7, NUDT11, and CYFIP2 can be used as independent prognostic factors for gliomas." (PMID 35614925, 2022). "After performing Cox univariate and LASSO Cox regression analyses, we selected three genes (NUDT7, NUDT11, and CYFIP2) to construct a risk score model that stratified glioma patients into low- and high-risk groups." (PMID 35614925, 2022). "The univariate Cox regression analysis of these genes showed that NUDT7, NUDT11, and CYFIP2 are all protective factors with a hazard ratio (HR) of less than 1 for the OS of glioma patients." (PMID 35614925, 2022). "The results showed that NUDT7, NUDT11, and CYFIP2 were all protective factors for OS in glioma patients." (PMID 35614925, 2022). "al. identified that gene expression of CYFIP2, when used together with two additional genes, could be used as a prognostic biomarker in glioma, similar to the findings in this study." (PMID 38473425, 2024). "Three proteins, CA9, CYFIP2, and LGALS3BP, were found to be associated with glioma progression and, in univariate analysis, could be used as prognostic markers." (PMID 38473425, 2024). "Nevertheless, further functional analyses are needed to understand the role CYFIP2 plays in glioma." (PMID 38473425, 2024). "Together as a panel, CA9, CYFIP2, and LGALS3BP were able to be used as a multi-gene prognostic index, highlighting the utility of these three molecules for predicting prognoses of glioma patients." (PMID 38473425, 2024). "Recently, the effect of m7G RNA methylation regulators on glioma prognosis has been investigated, where three genes (NUDT7, NUDT11 and CYFIP2) have been proposed as promising prognostic biomarkers for gliomas." (PMID 36012529, 2022).
microcephaly (3 papers, 2018 to 2025). A congenital or acquired developmental disorder in which the circumference of the head is smaller than normal for the person's age and sex. "The patients with CYFIP2 variants showed signs of microcephaly and began experiencing seizures around three to six months of age." (PMID 30687000, 2018).
schizophrenia (3 papers, 2015 to 2023). A major psychotic disorder characterized by abnormalities in the perception or expression of reality. "Further studies are needed to explore CYFIP2 as a potential target for the development of therapeutic interventions to compensate negative symptoms in schizophrenia related to morphological changes on pyramidal neurons." (PMID 37033658, 2023). "Thus, our study provides evidence that CYFIP2 is altered in prefrontal cortex with a possible impact on morphological alterations of pyramidal neurons in layers two and three in schizophrenia and the presence of negative symptoms." (PMID 37033658, 2023).
West syndrome (3 papers, 2018 to 2023). "Although the genetic associations between CYFIP2 and brain disorders are relatively unknown, two recent whole exome sequencing studies identified de novo hotspot variants of CYFIP2 (at the Arg87 residue) in patients diagnosed with West syndrome." (PMID 30687000, 2018).
autism spectrum disorder (2 papers, 2020 to 2025). A spectrum of developmental disorders that includes autism, and Asperger syndrome. "Two components of it (CYFIP2 and NCKAP1) are encoded by genes whose genetic mutations increase the risk for autism spectrum disorder (ASD) and related neurodevelopmental disorders." (PMID 39660913, 2025).
colorectal cancer (2 papers, 2021). A primary or metastatic malignant neoplasm that affects the colon or rectum. "Based on GRN results, the functional relationship between two genes pairs ({IL2R, CYFIP2} and {FOXM1, PPARA}) in colorectal cancer was found to be statistically significant by the differential co-expression method; this result was also confirmed by GRN and GSEA methods." (PMID 33968339, 2021).
developmental and epileptic encephalopathy, 65 (2 papers, 2022 to 2026). "Pathogenic variants in CYFIP2 cause developmental and epileptic encephalopathy 65 (DEE65) and have been predominantly investigated in the context of central nervous system dysfunction." (PMID 42035098, 2026).
endometrial cancer (2 papers, 2023 to 2024). Primary or metastatic malignant neoplasm involving the endometrium (mucous membrane that lines the endometrial cavity). "Chang’s study revealed that mutational dynamics and genetic variation, as well as aberrant DNA repair, tumor cell cycle control and apoptotic pathways were associated with CYFIP2 in endometrial cancer in the Taiwanese population." (PMID 37735711, 2023).
Obesity (2 papers, 2023 to 2024). Accumulation of substantial excess body fat. "For obesity and related metabolic disorders, data emphasized the potential of CYFIP2 as a pharmacotherapeutic target for treating obesity and other metabolic disorder." (PMID 37735711, 2023).
adenoma (1 paper, 2022). A neoplasm arising from the epithelium. "Despite a lack of direct evidence that inhibition of CYFIP2 contributes to CRC metastasis, a previous study has shown that CYFIP1, which shares 88% amino acid sequence similarity with CYFIP2, was lost in the majority of invasive colon adenocarcinoma tissues compared with noninvasive adenoma tissues." (PMID 35490216, 2022).
allergic disease (1 paper, 2015). An immune response that occurs following re-exposure to an innocuous antigen, and that requires the presence of existing antibodies against that antigen. "It is possible that CYFIP2 is implicated in a common pathway shared by both KD and allergy, although more research regarding the functional effect of CYFIP2 (rs767007) SNP mutations would be required to confirm this hypothesis." (PMID 26619243, 2015).
anaplastic cancer (1 paper, 2025). "Regarding the downregulated genes in ATC, three of them, namely PRKCD, CYFIP2, and BLNK, were described to have tumor suppressor activity and their downregulation is in line with the more aggressive behavior that characterizes an anaplastic cancer." (PMID 40965626, 2025).
cervical cancer (1 paper, 2025). A primary or metastatic malignant neoplasm involving the cervix. "For example, in cervical cancer, NUAK2 knockdown reduced cell proliferation, migration, and expression of EMT markers via interaction with CYFIP2." (PMID 40770117, 2025).
childhood asthma (1 paper, 2015). "In a study of 492 Mexican children, rs17599222 in the gene CYFIP2 was found to be associated with childhood asthma." (PMID 26619243, 2015).
cutaneous melanoma (1 paper, 2022). A primary melanoma arising from atypical melanocytes in the skin. "In the cutaneous melanoma cell lines, MEL 04.01 and MEL 06.24, Nutlin-3 treatment increased significantly CDKN1A, CYFIP2 and PTCHD4 expression, whereas PIK3IP1 and MXD4 levels do not or hardly change." (PMID 36139642, 2022).
Encephalopathy (1 paper, 2022). Encephalopathy is a term that means brain disease, damage, or malfunction. "Except for RCC, current research about CYFIP2 was mainly concentrated on neurons and encephalopathy, and more attention should be paid to RA." (PMID 35898498, 2022).
glioblastoma multiforme (1 paper, 2012). "Editing levels of the Alu element sites in BRCA1 gene were increased, and those of the coding sequences in CYFIP2 and FLNA genes were reduced in glioblastoma multiforme brain tissue." (PMID 22859999, 2012).
Kawasaki disease (1 paper, 2019). A rare inflammatory disease characterized by an acute febrile, systemic, self-limiting, medium-vessel vasculitis primarily affecting children. "CYFIP2 (cytoplasmic FMR1-interacting protein 2) forms part of the VEGFA–VEGFR2 pathway and is associated in humans with susceptibility to Kawasaki disease and coronary artery lesions, interacting with PDE2A so that high-risk allele combinations account for 67% of cases in this human population." (PMID 31683933, 2019).
lung adenocarcinoma (1 paper, 2023). A carcinoma that arises from the lung and is characterized by the presence of malignant glandular epithelial cells. "In this study, we first explored expression patterns, diagnostic role and prognostic value of CYFIP2 in cancers, particularly in lung adenocarcinoma (LUAD)." (PMID 37735711, 2023).
lymphoma (1 paper, 2022). A malignant (clonal) proliferation of B- lymphocytes or T- lymphocytes which involves the lymph nodes, bone marrow and/or extranodal sites. "In addition, CYFIP2 has also been found to affect lymphoma progression after undergoing epigenetic modifications." (PMID 35898498, 2022).
multiple sclerosis (1 paper, 2022). A progressive autoimmune disorder affecting the central nervous system resulting in demyelination. "CYFIP2 is highly abundant in CD4+ cells from multiple sclerosis patients and is involved in T cell adhesion, and ABLIM3 is a component of adherent junctions with actin‐binding activity." (PMID 35124891, 2022).
Prader-Willi syndrome (1 paper, 2019). "CYFIP2 is a homolog of CYFIP1 which is one of four paternally-deleted genes in patients with Type I Prader-Willi Syndrome (PWS), a neurodevelopmental disorder whereby 70% of cases involve paternal 15q11-q13 deletion." (PMID 31324746, 2019).
sarcoma (1 paper, 2023). A usually aggressive malignant neoplasm of the soft tissue or bone. "We further found that overexpression of CYFIP2 generally predicted good prognosis for patients with tumors, such as LUAD, thymoma, sarcoma, PDAC, clear cell RCC, and BC." (PMID 37735711, 2023).
Seizure (1 paper, 2021). A seizure is an intermittent abnormality of nervous system physiology characterized by a transient occurrence of signs and/or symptoms due to abnormal excessive or synchronous neuronal activity in the brain. "Seizures are associated with mutations in CYFIP2, which interacts with FMRP, and FMRP appears to underlie enhanced mLTD in adult rats triggered by early-life seizures." (PMID 35036394, 2021).
tumor (16 papers, 2017 to 2025). "Afterwards, functional enrichment analysis uncovered that CYFIP2 was involved in tumor-associated and immune-related pathways." (PMID 37735711, 2023). "Taken together, our present study indicated that CYFIP2 was aberrantly expressed in various tumors and highly involved in tumor-associated and immune-related pathways." (PMID 37735711, 2023). "Our study also indicated that CYFIP2 potentially contributed to regulation of tumor-associated and immune-related pathways and regulated immune-related genes." (PMID 37735711, 2023). "The difference in CYFIP2 expression levels in different tumor types may reflect distinct underlying functions and mechanisms." (PMID 37735711, 2023). "All tumor immune microenvironment scores of LUAD were significantly related to the CYFIP2 expression level." (PMID 37735711, 2023). "The mechanisms whereby CYFIP2 acts in tumor development and drives immune infiltration have been poorly explored." (PMID 37735711, 2023). "The results showed that CYFIP2 was markedly downregulated in LUAD tumor tissue compared with normal tissue and paired adjacent normal tissues." (PMID 37735711, 2023). "Using the TIMER database, we further evaluated the relationships between CYFIP2 expression and six main types of tumor infiltrating immune cells of LUAD." (PMID 37735711, 2023). "In addition, the abnormal expression of CYFIP2 was linked with immune cells infiltration and may affect tumor immunity by acting on immune regulators and immune-related genes, which may provide a foundation for more precise and personalized immunotherapy in future." (PMID 37735711, 2023). "In contrast, the expression levels of CYFIP2 in the tumor tissues of BRCA (P < 0.001), CHOL (P < 0.001), PRAD (P < 0.001) and THCA (P < 0.001) were significantly higher than the corresponding control tissues." (PMID 37735711, 2023). "CYFIP2 activates the cell death program to inhibit the proliferation of tumor cells, indicating that CYFIP2 is a potent tumor suppressor." (PMID 35614925, 2022). "In addition, the promoter methylation of CYFIP2 in tumor tissues of TCGA-LUAD was significantly lower than that of normal tissues adjacent to the cancer regardless of different clinical stages, N stages, gender, age and smoking status." (PMID 37735711, 2023). "Recent studies have shown that CYFIP2 is also closely related to tumor initiation and progression." (PMID 37735711, 2023). "The expression levels of CYFIP2 in the tumor tissues of BLCA (P < 0.001), ESCA (P < 0.001), KICH (P < 0.001), KIRC (P < 0.001), KIRP (P < 0.001), LUAD (P < 0.01), LUSC (P < 0.001), and UCEC (P < 0.05) were significantly lower than the corresponding control tissues." (PMID 37735711, 2023). "In a word, possible mechanisms through which CYFIP2 might influence tumor immunity are worthy of in-depth study." (PMID 37735711, 2023). "Our results suggested that CYFIP2 may serve as a prognostic cancer biomarker for determining prognosis and might be a promising therapeutic strategy for tumor immunotherapy." (PMID 37735711, 2023). "In this study, we suggested that CYFIP2 might be a promising therapeutic strategy for tumor immunotherapy." (PMID 37735711, 2023). "Then, we evaluated the expression of CYFIP2 in tumor tissues using the HPA database." (PMID 37735711, 2023). "In addition, we uncovered the landscape of CYFIP2 expression in tumor immunity and microenvironment through the correlation analysis of CYFIP2 expression with immune cell infiltration, immune regulators, and immune-related genes (chemokines, chemokines receptors, and MHC genes)." (PMID 37735711, 2023). "CA9, CYFIP2, and LGALS3BP levels were found to significantly increase as tumour grade increased (p < 0.05)." (PMID 38473425, 2024). "Correspondingly, there were some genes that were part of the CAP formation genes, such as NCBP3, NUDT4, CYFIP2, SNUPN, and EIF4E2, which were weakly expressed in most tumor tissues and highly expressed in normal tissues." (PMID 36226166, 2022).
tumor (continued). "The downregulated expression of IL-1, CTSW, NR1H3 and CCR8 (with HR < 1) indicated these molecules as tumor suppressors, whereas the upregulated expression levels of LY86, RABGEF1, CYFIP2 and SERINC3 (with HR > 1) indicated these molecules as oncogenes." (PMID 33816214, 2020). "Additionally, genes like COL4A1, PLOD2, and PXDN, which participate in extracellular matrix remodeling, alongside immune-related genes such as CYFIP2, EMP3, and HLA-B, are instrumental in modulating the tumor microenvironment and facilitating immune evasion." (PMID 39949776, 2025). "Activation of genes related to this pathway (CSF2, SERPINE1, PDGFD, CYFIP2, IL7R, MYB, CSF1) can promote tumor cell proliferation and survival, and may also affect immune cells in the TME." (PMID 41328768, 2025). "We found that several tumor infiltrating immune cells (Act_B cells, Imm_B cells, macrophage cells, Th1 cells, Tfh cells, CD8 + cells, pDC cells, CD4 + cells and Th17 cells) were correlated with the expression of CYFIP2 in cancers using TISIDB." (PMID 37735711, 2023). "However, the mechanisms by which CYFIP2 may affect tumor immunity have not been thoroughly investigated by biological experiments." (PMID 37735711, 2023).
cancer (15 papers, 2016 to 2025). A tumor composed of atypical neoplastic, often pleomorphic cells that invade other tissues. "Though CYFIP2 exhibits a high level of similarity to CYFIP1, its biological significance is ambiguous because CYFIP2 expression can be either a protective prognostic factor or a risk factor depending on the specific cancer type." (PMID 39930469, 2025). "We performed comparative analysis of CYFIP2 using cBioPortal database to figure out genomic mutation of CYFIP2 in different cancers." (PMID 37735711, 2023). "Then, we evaluated the clinical utility of CYFIP2 by studying its associations with different clinicopathological characteristics and potential role in the diagnosis and prognosis of different cancers." (PMID 37735711, 2023). "CYFIP2 was positively associated with most immune stimulators and immune inhibitors in different cancers." (PMID 37735711, 2023). "In the OS analysis, cox regression of 33 tumors revealed that CYFIP2 expression was substantially linked with OS in six cancers: KIRC, LGG, PAAD, SKCM, and THYM as protective factors, and UCEC as a risk factor." (PMID 35898498, 2022). "In the DSS analysis, Cox regression of 33 tumors revealed that CYFIP2 expression was substantially linked with DSS in 5 cancers: BLCA, KIRC, LGG, and PAAD were protective factors, whereas UCEC was a risk factor." (PMID 35898498, 2022). "CYFIP2 levels and immunological checkpoints were shown to be highly associated in a range of cancers, with mostly positive correlations in UVM and mostly negative correlations in BLCA, BRCA, COAD, HNSC, and PRAD, which were mostly negatively connected in UVM." (PMID 35898498, 2022). "Moreover, genetic alterations revealed that mutation of CYFIP2 was the main types of alterations in different cancers." (PMID 37735711, 2023). "However, the associations between CYFIP2 and different cancers remain inclusive." (PMID 37735711, 2023). "We then applied the TIMER2 approach to analyze human CYFIP2 expression levels in different cancer types based on TCGA data." (PMID 37735711, 2023). "Our study showed the correlation analysis between CYFIP2 expression and immune cell infiltration in pan-cancer." (PMID 37735711, 2023). "A high expression of CYFIP2 is related to cancer cells' sensitivity to nelarabine, Melphalan, and so on." (PMID 37089261, 2023). "CYFIP2-overexpressed cancer cells were demonstrated to be more sensitive to the following drugs: nelarabine, melphalan, idarubicin, and so on." (PMID 37089261, 2023). "To understand the expression and functions of CYFIP2 in different cancers, we should first know its expression in normal tissues." (PMID 37735711, 2023). "We used Kaplan–Meier Plotter, which is mainly based on Affymetrix microarray information from TCGA, to assess CYFIP2-related OS in different cancers." (PMID 37735711, 2023). "We looked into the relationship between CYFIP2 expression and pan-cancer patient prognosis, including overall survival (OS), disease-specific survival (DSS), and progression-free survival (PFS)." (PMID 35898498, 2022). "After further gene correlation analysis, immune infiltration analysis, and mouse gene expression validation, we finally selected CYFIP2 as the cut-in gene for pan-cancer analysis." (PMID 35898498, 2022). "The increased expression of WDR4, METTTL1, NUDT1, and CYFIP2 enhanced the sensitivity of some anti-cancer drugs such as hydroxyurea, L-asparaginase, 5-fluoro-deoxy-uridine 10mer, and chelerythrine." (PMID 36226166, 2022). "These included several candidate tumor suppressor genes, such as ABLIM1, CYFIP2, VPS13A, SERPINI1, TET2, HTRA4, UBE2L6, as well as oncogenes/genes implicated as biomarkers in other cancers, such as FAM65B and TCF7L2." (PMID 27385100, 2016).